NFS1 (NFS1 cysteine desulfurase)
Description:
[Isoform Mitochondrial]: Cysteine desulfurase, of the core iron-sulfur cluster (ISC) assembly complex, that catalyzes the desulfuration of L-cysteine to L-alanine, as component of the cysteine desulfurase complex, leading to the formation of a cysteine persulfide intermediate at the active site cysteine residue and participates in the [2Fe-2S] clusters assembly on the scaffolding protein ISCU. The persulfide is then transferred on the flexible Cys loop from the catalytic site of NFS1 to the surface of NFS1. After the NFS1-linked persulfide sulfur is transferred to one of the conserved Cys residues of the scaffold, a reaction assisted by FXN (By similarity). The core iron-sulfur cluster (ISC) assembly complex is involved in the de novo synthesis of a [2Fe-2S] cluster, the first step of the mitochondrial iron-sulfur protein biogenesis. This process is initiated by the cysteine desulfurase complex (NFS1:LYRM4:NDUFAB1) that produces persulfide which is delivered on the scaffold protein ISCU in a FXN-dependent manner. Then this complex is stabilized by FDX2 which provides reducing equivalents to accomplish the [2Fe-2S] cluster assembly. Finally, the [2Fe-2S] cluster is transferred from ISCU to chaperone proteins, including HSCB, HSPA9 and GLRX5 (By similarity). [Isoform Cytosolic]: May catalyze the desulfuration of L-cysteine to L-alanine as component of the cysteine desulfurase complex (NFS1:LYRM4), leading to the formation of a cysteine persulfide intermediate. Acts as a sulfur donor for MOCS3 by transferring the sulfur of the cysteine persulfide intermediate on MOCS3.
Synonyms: NIFS; HUSSY-08; IscS; COXPD52
Tractability: Small molecule: a structure with a bound ligand is known. PROTAC: ubiquitination databases record sites on it; its protein half-life has been measured.
Gene: Protein-coding gene on chromosome 20 (35,668,052 to 35,699,373, reverse strand). Ensembl gene ENSG00000244005.
Subcellular location: Mitochondrion (Isoform Mitochondrial); Cytoplasm, cytosol (Isoform Cytosolic); Nucleus; Cytoplasm, cytoskeleton, microtubule organizing center, centrosome
Subcellular location (Human Protein Atlas): Cytosol; Nucleoplasm
Pathways (Reactome):
Metabolism: Complex III assembly; Maturation of TCA enzymes and regulation of TCA cycle; Mitochondrial iron-sulfur cluster biogenesis; Molybdenum cofactor biosynthesis
Gene Ontology:
Molecular function: cysteine desulfurase activity; protein binding; protein homodimerization activity; sulfur carrier activity; pyridoxal phosphate binding
Biological process: [2Fe-2S] cluster assembly; iron-sulfur cluster assembly; [4Fe-4S] cluster assembly
Cellular component: centrosome; cytosol; mitochondrial [2Fe-2S] assembly complex; mitochondrial matrix; mitochondrion; nucleoplasm; nucleus; iron-sulfur cluster assembly complex
Genetic constraint (gnomAD): Loss-of-function variants: 17 observed, 38.1 expected, observed/expected ratio (o/e) 0.45, 90% interval 0.3 to 0.67. The upper end of that interval is the gene's LOEUF score, 0.67, which puts it in group 2 of 6, group 1 being the genes least tolerant of losing a copy. Missense variants: 429 observed, 506.85 expected, observed/expected ratio (o/e) 0.85, 90% interval 0.78 to 0.92. Synonymous variants: 186 observed, 182.61 expected, observed/expected ratio (o/e) 1.02, 90% interval 0.9 to 1.15.
Homologues: Orthologues: chimpanzee NFS1 (99% identical), dog NFS1 (94% identical), pig NFS1 (94% identical), macaque NFS1 (92% identical), rat Nfs1 (91% identical), mouse Nfs1 (91% identical), guinea pig NFS1 (84% identical), tropical clawed frog nfs1 (77% identical), zebrafish nfs1 (73% identical), Drosophila melanogaster Nfs1 (70% identical), Caenorhabditis elegans nfs-1 (61% identical). Paralogues in human: SCLY (33% identical).
Diseases named in the same sentence as NFS1 in open-access papers:
NFS1 is named in the same sentence as 35 diseases in open-access papers, as found by Europe PMC text mining. Sharing a sentence is not in itself a finding about the gene and the disease. The quoted sentences say what the papers report.
lung adenocarcinoma (19 papers, 2020 to 2025). A carcinoma that arises from the lung and is characterized by the presence of malignant glandular epithelial cells. "In a recent study, it was found that lung adenocarcinoma cells depend on high levels of the iron–sulfur cluster biosynthesis enzyme cysteine desulfurase (NFS1) to limit reactive iron that can cause lipid peroxidation." (PMID 33499222, 2021). "In lung adenocarcinoma, high expression of NFS1 has been shown to maintain iron–sulfur cluster cofactors in cancer cells, thereby resisting oxidative damage and avoiding ferroptosis." (PMID 41152153, 2025). "For example, the Fe-S cluster biogenesis enzyme NFS1 is highly expressed in lung adenocarcinoma, where it protects against the induction of ferroptosis by oxidative damage resulting from high oxygen." (PMID 40961184, 2025). "Modulating the expression of cysteine desulfurase (NFS1) to induce ferroptosis has shown potential in curtailing the progression of lung adenocarcinoma." (PMID 38317842, 2024). "NFS1 is found overexpressed in patients with lung adenocarcinoma, and increased levels of NFS1 promote growth of primary lung tumor cells in vitro, whereas NFS1 knockdown improves anticancer activity of ferroptosis-inducing compounds in lung cancer cells." (PMID 37132605, 2024). "Secondly, specific proteins in lung adenocarcinoma cells, such as NFS1, STYK1, and LSH, play important regulatory roles in the process of ferroptosis." (PMID 37946181, 2023). "NFS1 suppression sensitizes lung adenocarcinoma cells to ferroptosis by stimulating the iron-starvation response, stabilizing TfR1 mRNA and inhibiting FTH1 expression." (PMID 37325669, 2023). "For example, overexpression of the protein NFS1 in lung adenocarcinoma cells can promote tumor growth and reduce sensitivity to ferroptosis drugs." (PMID 37946181, 2023). "For example, lung adenocarcinomas select for overexpression of NFS1, which confers resistance to high oxygen tension and protects cells from ferroptosis in response to oxidative damage." (PMID 36876095, 2023). "They examined the NFS1 expression in different types of lung cancer by immunohistochemistry and found that the NFS1 expression was the highest in lung adenocarcinoma, followed by lung squamous cell carcinoma and small cell lung cancer." (PMID 34616505, 2021). "NFS1 is overexpressed in patients with lung adenocarcinoma, and upregulated NFS1 promotes growth of primary lung tumor cells in vitro." (PMID 34742351, 2021). "The iron–sulfur cluster biosynthetic enzyme NFS1 maintains the iron–sulfur co-factors level and serves as an upstream regulator to control the iron-starvation response and limit the effect of high levels of oxygen tension in a lung adenocarcinoma context." (PMID 37325669, 2023). "Inhibition of NFS1 can induce ferroptosis and slow tumor growth in lung adenocarcinoma." (PMID 34869304, 2021). "The inhibition of cysteine desulfurase NFS1, an enzyme that removes sulfur from cysteine, induced ferroptosis in lung adenocarcinoma cells." (PMID 40703196, 2025). "NFS1 cysteine desulfurase is under positive selection in lung adenocarcinomas and protects cancer cells from ferroptosis, a non-apoptotic form of cell death, in response to oxidative damage." (PMID 35008645, 2021). "Under the circumstance of intracellular ROS accumulation, the suppression of NFS1 can promote ferroptosis in lung adenocarcinomas, while the inhibition of NFS1 alone (without excessive ROS) has little effect on ferroptosis." (PMID 32685102, 2020).
colorectal cancer (14 papers, 2022 to 2025). A primary or metastatic malignant neoplasm that affects the colon or rectum. "NFS1 is a rate‐limiting enzyme in iron–sulfur cluster biosynthesis that is overexpressed in colorectal cancer compared to normal tissue and has been linked to a poor prognosis." (PMID 36776001, 2023). "Investigators have found that loss of Cysteine desulfurase (NFS1) significantly enhances the sensitivity of Colorectal cancer (CRC) cells to oxaliplatin, triggering PANoptosis through increased intracellular reactive oxygen species levels." (PMID 37864090, 2023). "For instance, in colorectal cancer, the increased cell death induced by cysteine desulfurase (NFS1) or Wilms tumor 1-associating protein (WTAP) depletion under oxaliplatin treatment cannot be completely reversed by any of the inhibitors of apoptosis, pyroptosis and necroptosis alone." (PMID 40721869, 2025). "Cysteine desulfurase (NFS1) deficiency significantly enhanced the sensitivity of colorectal cancer cells to oxaliplatin due to the synergistic effect of NFS1 deficiency with oxaliplatin treatment, triggering PANoptosis by increasing intracellular levels of reactive oxygen species." (PMID 36845112, 2023). "NFS1 deficiency could trigger PANoptosis to increase the sensitivity of colorectal cancer cells to oxaliplatin." (PMID 37313428, 2023). "For example, in colorectal cancer, phosphorylated cysteine desulfurase (NFS1) has been demonstrated to impair the chemosensitivity of oxaliplatin-based treatments through the inhibition of PANoptosis." (PMID 38322112, 2024). "A study based on the biological function of NFS1 found that its deletion significantly enhanced the sensitivity of colorectal cancer cells to oxaliplatin." (PMID 38877579, 2024). "Furthermore, a recent study revealed that inhibiting the enzyme NFS1 or its phosphorylation can enhance the sensitivity of colorectal cancer cells to oxaliplatin by promoting PANoptosis, leading to improved chemotherapy outcomes." (PMID 38501104, 2024). "A study used CRISPR-Cas9 to delete the gene for cysteine desulfurase (NFS1), a metabolic enzyme involved in energy production, in colorectal cancer cells (CRC)." (PMID 38169587, 2024). "However, the influence and regulation of cysteine desulfurase (NFS1), a rate-limiting enzyme in iron–sulfur (Fe–S) cluster biogenesis, in colorectal cancer (CRC) remain elusive." (PMID 35221331, 2022).
lung carcinoma (13 papers, 2020 to 2026). "Research has discovered that the growth of lung cancer cells in vivo is inhibited and that lung cancer cells are more susceptible to ferroptosis when NFS1 is reduced to increase the level of intracellular LIP." (PMID 41439136, 2026). "NFS1 suppression via RNAi in a lung cancer line increases cellular-free Fe2+, predisposing cells to a form of Fe-dependent cell death called ferroptosis." (PMID 39151727, 2024). "Indeed, the overexpression of NFS1 has been associated with the progression of various cancers, including lung cancer, colon cancer, gastric cancer, and pancreatic cancer." (PMID 40141425, 2025). "In the context of cancer, overexpression of NFS1, a component of the core Fe-S assembly complex, due to gene amplification is reported in lung cancer." (PMID 39151727, 2024). "NFS1 cysteine desulfurase can synthesize heme and iron-sulfur clusters from iron transported to mitochondria and suppress ferroptosis in lung cancer cells produced by oxidative stress damage." (PMID 38213172, 2024). "It has been reported that NFS1 is upregulated in lung cancer, thereby conferring cancer cells resistance to high oxygen tension by inhibiting the ferroptosis." (PMID 38700533, 2024). "Gene amplification revealed by our analysis of TCGA cohorts suggests a possible cancer-promoting role for FDX2 in OVC, analogous to NFS1 in lung cancers." (PMID 39151727, 2024). "Here, comparable to NFS1 amplification in lung cancer, we observed FDX2 gene amplification in a substantial fraction of ovarian cancer (OVC) cases, an observation not previously reported in other cancer types." (PMID 39151727, 2024). "Previous studies have demonstrated the significant upregulation of NFS-1 in lung cancer tissues and its ability to effectively mitigate hyperoxia-induced ferroptosis in lung cancer cells, its potential as a protective agent against ferroptosis in this context." (PMID 37728413, 2023). "In lung cancer, the overexpression of NFS1, one kind of iron-sulfur cluster biosynthetic enzyme, will sustain the iron-sulfur cluster expression, and inhibition of NFS1 leads to iron starvation and result in ferroptosis." (PMID 35959461, 2022). "NFS1, an enzyme involved in synthesizing iron-sulfur clusters using sulfur from cysteine, protects cells from ferroptosis in lung cancer." (PMID 32760210, 2020). "Since recent studies have demonstrated that NFS1 is upregulated in lung cancer cells, we speculated that these two compounds might suppress the proliferation of A549 cells by inhibiting NFS1 activity." (PMID 40141425, 2025). "In lung cancer, depletion of NFS1 in combination with cysteine transport inhibition disrupts ISCs, inducing ferroptosis and impairing tumor growth, and may represent a potential therapeutic intervention by targeting NFS1." (PMID 40822970, 2025). "Therefore, Compound 53 could be used to explore the biological roles of NFS1 and serve as a lead compound for the design of therapeutic agents for the treatment of lung cancer." (PMID 40141425, 2025). "Therefore, NFS1 can regulate ferroptosis in lung cancer cells negatively." (PMID 34616505, 2021). "First, the expression levels of NFS1 in BEAS-2B normal lung epithelial cells and A549 lung cancer cells were determined." (PMID 40141425, 2025). "By contrast, unlike Erastin, Compound 53 did not significantly increase cellular ROS levels, consistent with a previous report that NFS1 knockdown via siRNA did not affect ROS levels in lung cancer cells." (PMID 40141425, 2025).
breast cancer (7 papers, 2022 to 2025). A primary or metastatic malignant neoplasm involving the breast. "High NFS1 expression is associated with poor prognosis, increased tumor aggressiveness, and resistance to ferroptosis in breast cancer, highlighting the role in tumor progression." (PMID 40822970, 2025). "Specifically, in hypoxic breast cancer cells, CA IX targeting, together with depletion of cysteine desulfurase NFS1 or Erastin treatment, increases ferroptosis." (PMID 40569831, 2025). "Targeting CA9 enhances ferroptosis driven by NFS1 cysteine desulfurase (NFS1) inhibition in a pH-dependent manner in human breast cancer cells." (PMID 38844964, 2024). "Recent experiments showed that certain breast cancer lines can be potentiated towards iron overload-induced ferroptosis through the inhibition of NFS1 (cysteine desulfurase), the protein responsible for sulfur supply in the ISC biosynthetic pathway." (PMID 35563576, 2022). "Further, NFS1 knockdown inhibits cancer cell proliferation in oxygen-rich environments and prevents circulating cancer cells exposed to high oxygen levels from forming metastases in a murine mammary tumour model." (PMID 40797101, 2025).
Friedreich ataxia (4 papers, 2016 to 2026). An inherited condition that affects the nervous system and causes movement problems. "Proteins from the IscS and Nfs1 families also differ dramatically in their behaviour with respect to frataxin, the protein responsible for Friedreich’s ataxia." (PMID 27427956, 2016).
iron deficiency (3 papers, 2014 to 2026). "Depletion of NFS1 cysteine desulfurase in mitochondria reduces the synthesis of iron-sulfur clusters, triggering a feedback response to iron deficiency that increases iron uptake and enhances sensitivity to ferroptosis." (PMID 41513612, 2026). "NFS1 cysteine desulfurase is responsible for removing sulfur from cysteine, although its action depends on the iron content of the mitochondrion, therefore, iron deficiency or overload have a deep impact on iron-sulfur cluster biogenesis." (PMID 31067791, 2019).
gastric cancer (2 papers, 2025). A primary or metastatic malignant neoplasm involving the stomach. "The current work has further elucidated the expression and functional implication of cysteine desulfurase (NFS1) in gastric cancer (GC), the prognostic value, and therapeutic target because of the interaction with tumor immune infiltration and ferroptosis." (PMID 40822970, 2025).
hepatocellular carcinoma (2 papers, 2021 to 2022). A malignant tumor that arises from hepatocytes. "In particular, as prognostic indicators, ABCC1 and NFS1 have also been included in the survival prediction model of hepatocellular carcinoma, implying their robust roles in survival prediction." (PMID 34276794, 2021). "It is reported that in the prognosis model of hepatocellular carcinoma, the genes (NFS1, CISD1, ACSL3, NQO1, SLC7A11, GPX4) that can protect hepatocytes with ferroptosis and the genes (ACACA, CARS, G6PD, SLC1A5) that induce ferroptosis are all up-regulated in HCC, and are related to poor prognosis." (PMID 36387286, 2022).
prostate carcinoma (2 papers, 2021 to 2025). A carcinoma that arises from epithelial cells of the prostate gland. "Similarly, elevated NFS1 expression correlates with poor outcomes in prostate cancer, and targeting NFS1 may enhance the sensitivity of cancer cells to ferroptosis-based therapies." (PMID 40822970, 2025).
acute myeloid leukemia (1 paper, 2025). Acute myeloid leukemia (AML) is a group of neoplasms arising from precursor cells committed to the myeloid cell-line differentiation. "In acute myeloid leukemia, It has been shown REV increased the expression of hsa-miR-335-5p while decreased the expression of NFS1 and GPX4; it increased ferroptosis in AML cells through the Hsa-miR-335-5p/NFS1/GPX4 pathway in a manner dependent on ROS." (PMID 40552277, 2025).
diabetes (1 paper, 2025). "Interestingly, diabetes or HG/PA treatment led to decreased S‐sulfhydration levels of NFS1 and ISCU in cardiomyocytes, thereby reducing de novo synthesis of Fe–S clusters." (PMID 39495652, 2025).
diabetic cardiomyopathy (1 paper, 2025). Diabetic cardiomyopathy is a disorder of the heart muscle in people with diabetes. "Supplementing with hydrogen sulfide (H2S) enhances Fe–S cluster synthesis via S‐sulfhydration of cysteine desulfurase (NFS1) at C383, preserving mitochondrial and nuclear DNA integrity and ameliorating diabetic cardiomyopathy (DCM)." (PMID 39495652, 2025).
hypertrophic cardiomyopathy (1 paper, 2010). A condition in which the myocardium is hypertrophied without an obvious cause. "It is interesting to note that Nfs1 is an aminotransferase with a cysteine desulfurase function implicated in Freidrich's ataxia, a complex disease often associated with a hypertrophic cardiomyopathy phenotype." (PMID 20937113, 2010).
melanoma (1 paper, 2022). A malignant, usually aggressive tumor composed of atypical, neoplastic melanocytes. "In contrast, ALOX5, CISD1, ATP5MC3, NFS1, EMC2, ZEB1 are highly expressed in normal tissues, and they are related to the good prognosis of melanoma patients." (PMID 36313708, 2022).
ovarian carcinoma (1 paper, 2022). A malignant neoplasm originating from the surface ovarian epithelium. "The OS of ovarian cancer patients prolonged with the high-expression of ATG7, G6PD, SLC3A2, MAP1LC3C and PTGS2, but shrank with the increased expression of NFS1, VDAC2, ACSL3." (PMID 35039008, 2022).
stomach adenocarcinoma (1 paper, 2025). "NFS1 expression was higher in most types of tumors, including stomach adenocarcinoma." (PMID 40822970, 2025).